GDF15 (growth differentiation factor 15)
Diseases named in the same sentence as GDF15 in open-access papers (continued):
Sharing a sentence is not in itself a finding about the gene and the disease.
atherosclerosis (continued). "GDF-15 deficiency attenuates atherosclerosis by regulating interleukin-6 dependent inflammatory response to vascular injury." (PMID 26273671, 2015). "Overall GDF-15 levels are increased in cardiovascular disease patients and enhance the risk of atherosclerosis." (PMID 26273671, 2015). "GDF-15 deficiency results in inhibition of atherosclerosis in mice despite an inhibition of apoptotic processes and an increase in cell density in atherosclerotic lesions." (PMID 26273671, 2015). "Here we show for the first time that GDF‐15 deficiency results in inhibition of atherosclerosis progression in hypercholesterolemic mice despite an inhibition of apoptotic processes and an increase in cell density in atherosclerotic lesions." (PMID 23316317, 2012). "The aim of this review is to synthesize current evidence on the association between GDF-15 and markers of subclinical atherosclerosis, and to evaluate whether GDF-15 may serve as an integrative biomarker reflecting shared cardiometabolic pathways." (PMID 41597417, 2026). "In this population, uremia, inflammation, and malnutrition may explain the association between atherosclerosis and increased levels of GDF-15." (PMID 41597417, 2026). "The differences between groups could be explained by age, antiretroviral therapy duration, metabolic health, and systemic inflammation, which are more frequent in older patients and modulate the GDF-15-atherosclerosis association in HIV populations." (PMID 41597417, 2026). "In metabolic disorders, GDF-15’s association with subclinical atherosclerosis was present, but inconsistent, since this association tended to be stronger in patients with advanced metabolic disturbances, and weaker in younger patients or those with better metabolic control." (PMID 41597417, 2026). "Beyond its established prognostic value in cardiovascular diseases (CVD) and HF, recent evidence suggests that GDF-15 may also reflect subclinical atherosclerosis, potentially improving early risk stratification in obese and HF populations." (PMID 41597417, 2026). "Additionally, an apoptosis pathway was observed with proteins TRAIL-R2, TNF-R1, and GDF-15, which are linked to the regulation of programmed cell death in atherosclerosis (GO:0043065, GO:0042981, GO:0008625)." (PMID 39658319, 2025). "On the other hand, other research shows that GDF15 could exert protective effects in atherosclerosis, as in models where GDF15 deficiency increases macrophage accumulation and destabilizes plaques." (PMID 40837873, 2025). "Serum concentrations of GDF-15 may mediate the association between fast eating speed and atherosclerosis." (PMID 39019981, 2024). "The exact cutoff for the GDF-15 level that determines the association between fast eating speed and atherosclerosis in the general population is unknown." (PMID 39019981, 2024). "Additionally, given the role of GDF15 in atherosclerosis and CV disease, we analyzed the impact of the rs1054564 genetic variants on subclinical atherosclerosis." (PMID 39596055, 2024). "Since an inconsistent correlation was reported between the white cell count and carotid atherosclerosis, clarifying the influence of GDF-15 on atherosclerosis progression might identify a novel mechanism underlying atherosclerosis progression." (PMID 39019981, 2024). "Furthermore, GDF15 levels have been related to surrogate indicators of atherosclerosis and have been proposed as predictors of both all-cause and CV mortality." (PMID 39596055, 2024). "They found a significant positive association between GDF-15 and atherosclerosis." (PMID 38396781, 2024). "A significant positive association between GDF-15 concentrations and atherosclerosis was observed." (PMID 37371667, 2023). "Serum concentrations of GDF-15 may be positively associated with atherosclerosis as evaluated by CIMT." (PMID 37371667, 2023). "Since mitochondrial stress and dysfunction increase GDF-15 levels, GDF-15 could be positively associated with atherosclerosis." (PMID 37371667, 2023).
atherosclerosis (continued). "Serum GDF-15 concentration could be an efficient tool for estimating the risk of atherosclerosis among older individuals with normal weight." (PMID 37371667, 2023). "Therefore, although a strong significant association between GDF-15 concentrations and atherosclerosis was observed in the present study, the correlation between GDF-15 concentrations and continuous values of CIMT was weak." (PMID 37371667, 2023). "This suggests that anIL-1ß/GDF-15-associated immunity pathway may lead to atherosclerosis and,consequently, CAD." (PMID 39077481, 2023). "Indeed, cultured peritoneal macrophages stimulated by oxidized LDL exhibit an increased GDF15 mRNA level, suggesting that elevated GDF15 is associated with atherosclerosis progression." (PMID 36992609, 2023). "GDF-15 concentrations could be positively associated with atherosclerosis and an indicator of angiogenesis activity." (PMID 37371667, 2023). "A significant positive association between GDF-15 and atherosclerosis was observed." (PMID 37371667, 2023). "Individuals with higher serum GDF-15 levels might have higher macrophage activity, indicating a higher risk of developing atherosclerosis." (PMID 37371667, 2023). "Those factors could act as determinants of the association between GDF-15 concentrations and atherosclerosis." (PMID 37371667, 2023). "Serum GDF-15 concentrations could help us to estimate the risk of atherosclerosis by indicating the status of cellular energy balance, which is related to mitochondrial activity among comparative healthy older individuals." (PMID 37371667, 2023). "However, in the present study, serum GDF-15 concentration was significantly associated with atherosclerosis among individuals with normal BMI." (PMID 37371667, 2023). "Serum GDF-15 concentration might reflect factors associated with cellular energy balance that might lead to the progression of atherosclerosis, even among older individuals with normal weight and normal thyroid hormone levels." (PMID 37371667, 2023). "The authors have proposed that high GDF15 may be mediated by asymptomatic atherosclerosis, another cause of chronic low-grade inflammation." (PMID 36243733, 2022). "While GDF15 is a cardiovascular risk factor, whether GDF15 directly contributes to the development of atherosclerosis has not been established, and the precise relationships between GDF15 and atherosclerosis are not fully understood." (PMID 36444166, 2022). "In many cardiovascular diseases (such as hypertrophy, heart failure, atherosclerosis, endothelial dysfunction), obesity, insulin resistance, diabetes, and chronic kidney diseases are associated with increased GDF‐15 and linked with the progression and prognosis of the disease condition." (PMID 35846052, 2022). "In addition, elevated circulating GDF-15 levels are suggested as a potential biomarker for cardiovascular risk and outcome as it is directly linked to atherosclerosis progression." (PMID 35600479, 2022). "However, GDF-15 deficiency protects against atherosclerosis by attenuating C-motif chemokine receptor 2-mediated macrophage chemotaxis." (PMID 34394348, 2021). "Growth differentiation factor (GDF)-15 is linked to inflammation, cancer, and atherosclerosis." (PMID 34920697, 2021). "In contrast, bone marrow chimeras with loss of GDF15 expression in the bone marrow compartment are protected from the development of atherosclerosis and exhibit reduced macrophage content in atherosclerotic plaques, suggesting a potential proinflammatory role for GDF15 in this setting." (PMID 32310257, 2020). "To address the question of whether loss of GDF‐15 affects the development and progression of atherosclerosis in vivo, we investigated sections of the aortic arch in GDF‐15−/−/apoE−/− and GDF‐15+/+/apoE−/− mice." (PMID 23316317, 2012).
atherosclerosis (continued). "Therefore, GDF-15 levels may influence the association between fast eating speed and atherosclerosis." (PMID 39019981, 2024). "Therefore, if there is greater activity of monocyte/macrophage lineage cells due to high GDF-15 levels, fast eating speed may be positively associated with atherosclerosis by indicating the presence of habitual glucose spikes." (PMID 39019981, 2024). "Therefore, thyroid function may act as a strong confounder regarding the role of GDF-15 in the association between eating speed and atherosclerosis." (PMID 39019981, 2024). "Therefore, measuring GDF-15 levels may be an efficient means of evaluating atherosclerosis risk as related to eating speed." (PMID 39019981, 2024). "Therefore, individuals with higher levels of serum GDF-15 might have greater macrophage activity, indicating a higher risk of developing atherosclerosis." (PMID 39019981, 2024). "Therefore, we hypothesized that fast eating speed would be significantly positively associated with atherosclerosis but only in people with high GDF-15 levels." (PMID 39019981, 2024). "Levels of CRP might affect the association between GDF-15 concentrations and atherosclerosis." (PMID 37371667, 2023). "However, inconsistent reports show that a deficiency of GDF15 prevents atherosclerosis." (PMID 34445593, 2021). "However, GDF-15 deficiency in leukocytes protects against atherosclerosis." (PMID 26273671, 2015). "All results about the relationship between GDF-15 and subclinical atherosclerosis should be interpreted taking into account several important confounders." (PMID 41597417, 2026). "The correlation between GDF-15 concentrations and markers of subclinical atherosclerosis showed a significant variability among different cohorts." (PMID 41597417, 2026). "In atherosclerosis, macrophage activation facilitates the uptake of oxidized low-density lipoprotein and secretion of GDF-15, contributing to the atherosclerotic plaque formation and to the local inflammation." (PMID 41597417, 2026). "PubMed, Embase, Scopus, and Web of Science were searched for human studies evaluating the correlation between markers of subclinical atherosclerosis and GDF-15 concentration." (PMID 41597417, 2026). "During the progression of atherosclerosis, GDF-15 expression is markedly increased, particularly within macrophages of atherosclerotic plaques in both humans and mice." (PMID 41590509, 2026). "Given the overlapping pathophysiological mechanisms shared by PAD and cardiac disease, including endothelial dysfunction, metabolic dysregulation, and atherosclerosis, there is important value in investigating GDF15’s prognostic utility in patients with PAD." (PMID 40806859, 2025). "Clinically, elevated GDF15 levels have been observed in individuals with vascular dysfunction, atherosclerosis, and thrombotic conditions." (PMID 40806859, 2025). "Lipid markers, including Lp-PLA2 and oxylipins, elucidate lipid metabolism’s contribution to atherosclerosis, while inflammatory biomarkers like TNFα, IL-6, GDF-15, and PTX3 highlight the role of chronic inflammation in CVD progression." (PMID 40244022, 2025). "Beyond HF, GDF-15 plays a role in inflammation-driven cardiovascular conditions, such as atherosclerosis, by mitigating foam cell formation and suppressing lipid accumulation." (PMID 40244022, 2025). "Clinically, elevated circulating GDF15 levels have been reported in individuals exhibiting vascular dysfunction, atherosclerosis, and thrombotic disorders." (PMID 40723863, 2025). "In advanced atherosclerosis, the available data on GDF-15 are contradictory; overexpression of GDF-15 reduces plaque size, while lack of GDF-15 improves plaque stability by impairing macrophage migration and enhancing collagen deposition." (PMID 37548881, 2024). "The usefulness of blood TGF-β isoforms and GDF-15 measurements in the assessment of EC damage and atherosclerosis onset should be further clarified in more carefully selected patient groups." (PMID 38396781, 2024).
atherosclerosis (continued). "The inflammatory and angiogenic effects of GDF-15 in atherosclerosis are controversial, and its correlation with the long asymptomatic phase of the disease is not well understood." (PMID 37548881, 2024). "In this review, we will focus on the TGF-β superfamily cytokines, TGF-β1,2,3 isoforms and GDF-15, because new information has been discovered in recent years about their role in the development of atherosclerosis." (PMID 38396781, 2024). "Given that macrophage accumulation and endothelial dysfunction contribute to atherosclerosis, GDF15 plays an important role in PAD development and progression." (PMID 38361633, 2024). "GDF-15 also influences lipid metabolism, crucial in atherosclerosis, by reducing lipid accumulation and foam cell formation, potentially through activation of the peroxisome proliferator-activated receptor β/δ (PPARβ/δ) pathway." (PMID 38791250, 2024). "In the late stage of atherosclerosis, GDF15 prevents atherosclerosis by inhibiting monocyte chemotaxis and macrophage activation." (PMID 38333748, 2024). "GDF-15 has emerged as a significant player in mechanisms involved in atherosclerosis and macrophage function." (PMID 39000420, 2024). "(2011) demonstrated that deletion of GDF15 in murine models had a beneficial effect in both early and late atherosclerosis development, indicating the importance of this protein in plaque development and progression." (PMID 38361633, 2024). "Some work has investigated the levels of GDF-15 in the blood of different groups of people in relation to atherosclerosis." (PMID 38396781, 2024). "The results suggest that GDF-15 has a variety of protective effects against atherosclerosis, including inhibition of monocyte infiltration into the arterial wall and inhibition of plaque development and growth." (PMID 38396781, 2024). "In humans, serum levels of GDF-15 have been shown to be elevated in both subclinical and clinical forms of atherosclerosis." (PMID 37548881, 2024). "In this study, we explored the impact of selected SNPs from a chromosome 19 locus containing the GDF15 gene on metabolic disturbances and subclinical atherosclerosis." (PMID 39596055, 2024). "In this study, we analyzed the impact of selected GDF15 SNPs on metabolic disturbances and subclinical atherosclerosis." (PMID 39596055, 2024). "In the following, we will discuss what has been found in recent years in the field of the influence of individual TGF-β isoforms and GDF-15 on the initiation and development of atherosclerosis." (PMID 38396781, 2024). "Our results show that GDF-15 is not only a useful biomarker of inflammation but can also predict early signs of asymptomatic atherosclerosis, especially in elderly people with chronic systemic inflammation associated with aging (inflammaging)." (PMID 37548881, 2024). "In conclusion, it seems that GDF-15 is not only a useful biomarker of inflammation but can also predict early signs of asymptomatic atherosclerosis, especially in elderly people with chronic systemic inflammation associated with aging (inflammaging)." (PMID 37548881, 2024). "The precise mechanism by which GDF-15 contributes to the interaction between macrophages and atherosclerosis remains uncertain." (PMID 39000420, 2024). "GDF15 is a protective cytokine that prevents atherosclerosis development and vascular endothelial injury." (PMID 38333748, 2024). "This suggests a potential immunomodulatory role of GDF-15 in the progression of atherosclerosis by reducing the proinflammatory plaque surroundings." (PMID 39000420, 2024). "Compared to the participants with low GDF-15, those with high GDF-15 had significantly higher ORs of atherosclerosis in the sex- and age-adjusted model (model 1), thyroid hormone–adjusted model (model 2), and metabolic factor–adjusted model (model 3)." (PMID 39019981, 2024).
atherosclerosis (continued). "Among participants with a low GDF-15 level, the sex- and age-adjusted (model 1) ORs (95%CI) for atherosclerosis were 1.69 (0.74, 3.86) for high BMI and 2.09 (0.64, 6.82) for high HbA1c." (PMID 39019981, 2024). "Studies conducted in vitro and in vivo have shown that the combination of GDF15 with oxidized lipid molecules increases the activity of macrophages, contributing to the progression of atherosclerosis." (PMID 39329916, 2024). "This association is compatible with the results of the present study showing that participants with a high GDF-15 level had significantly higher ORs of atherosclerosis than those with a low GDF-15 level." (PMID 39019981, 2024). "In recent years, the involvement of TGF-β and GDF-15 in atherosclerosis has been intensively analysed." (PMID 38396781, 2024). "Systemic inflammation also leads to progression of atherosclerosis and insulin resistance, and changes in metabolic hormonal activity such as insulin growth factor and growth differentiation factor 15 (GDF‐15), which also contribute towards worsening frailty." (PMID 37586848, 2023). "Therefore, the association between GDF-15 and atherosclerosis could be strongly confounded by age." (PMID 37371667, 2023). "The age-adjusted ORs and 95% CIs for the logarithmic GDF-15 and atherosclerosis were 2.61 (0.88, 7.72) for men and 2.71 (0.80, 9.19) for women, respectively." (PMID 37371667, 2023). "The sex- and age- adjusted OR and 95% CI for the logarithmic value of GDF-15 and atherosclerosis were 3.04 (1.26, 7.34)." (PMID 37371667, 2023). "The sex- and age- adjusted OR and 95% CI for the logarithmic value of GDF-15 and atherosclerosis were 2.62 (1.67, 5.87)." (PMID 37371667, 2023). "In the sex- and age-adjusted model (Model 1), the odds ratio (OR) (95% confidence interval (CI)) for the logarithmic value of GDF-15 and atherosclerosis was 2.62 (1.67, 5.87)." (PMID 37371667, 2023). "The sex-, age- and WBC count-adjusted OR and 95% CI for the logarithmic value of GDF-15 and atherosclerosis was 2.70 (1.07, 6.77)." (PMID 37371667, 2023). "The sex- and age-adjusted ORs and 95% CI for atherosclerosis and logarithmic GDF-15 values were 5.36 (1.17, 25.54) for participants aged < 65 years and 2.04 (0.78, 5.28) for those aged ≥ 65 years." (PMID 37371667, 2023). "By preventing CCR2-mediated chemotaxis and controlling cell death, GDF-15 deletion has a positive effect on both early and late stages of atherosclerosis." (PMID 36864452, 2023). "During the initial phase of atherosclerosis, researchers have observed smaller atherosclerotic lesions in GDF-15−/− mice; however, this difference disappeared after 12 weeks." (PMID 37900593, 2023). "Further studies are needed to elucidate the central role of GDF-15 in the pathophysiology of early atherosclerosis and MI in the young population." (PMID 37888100, 2023). "This suggests a crucial involvement of GDF-15 in themechanism of atherosclerosis development and progression." (PMID 39077481, 2023). "GDF-15 promotes indirect proinflammatory effects in models of atherosclerosis, while GDF-15 mediates anti-inflammatory effects in mice with acute myocardial infarction." (PMID 37371667, 2023). "It has been shown that GDF15 is regarded as a strong and independent predictor of mortality and disease progression in patients with atherosclerosis and coronary artery disease." (PMID 36444166, 2022). "GDF-15 showed its broad anti-inflammatory function in the animal models of myocardial infarction, atherosclerosis and rheumatoid arthritis." (PMID 35784345, 2022). "GDF15 was originally identified as a factor overexpressed in activated macrophages to regulate inflammation, which is involved in all stages of atherosclerosis, from its initiation and progression to its thrombotic complications." (PMID 36444166, 2022).